BRCA1 (BRCA1 DNA repair associated)
Diseases named in the same sentence as BRCA1 in open-access papers (continued):
Sharing a sentence is not in itself a finding about the gene and the disease.
tumor (continued). "NCCN also suggests biomarker-guided treatments for tumor mutation burden-high and RET fusion-positive tumors, and ESMO suggests treatment for patients with BRCA1/2 or PALB2 mutations." (PMID 38838500, 2024). "BRCA1 is a tumor suppressor gene located on the long arm of Chromosome 17 at Position 21 and plays a major role in preserving chromosomal stability." (PMID 39502381, 2024). "HER-2, two tumour suppressor genes; breast cancer gene 1 (BRCA1), and breast cancer gene 2 (BRCA 2), and cell angiogenesis gene mTOR (all primers were purchased from willowfort.co.uk) were tested in the present study." (PMID 39103402, 2024). "Leveraging the BRCA1-mutated MOLT4 cell line, our data confirmed that the compound 180055 is capable of significantly inhibiting tumor cell proliferation in both in vitro and in vivo models, corroborating the synthetic lethality principle." (PMID 39695097, 2024). "As both BRCA1 and RNF43 reside on chromosome 17q, the LOH observed across the region encompassing both these tumor suppressor genes confirms that both BRCA1 and RNF43 had biallelic inactivation." (PMID 38063999, 2024). "As CHORD provides subtype-level resolution for HRD, we also mapped CHORD predictions to tumor types to see how the distribution of BRCA1-type HRD compared with that of BRCA2-type HRD." (PMID 39485057, 2024). "Based on the HR for TNBC and HGSOC related to BRCA1 constitutional methylation, women diagnosed with these malignancies and found to harbor constitutional methylation may be considered at increased risk of a secondary tumor and could, therefore, be referred for special surveillance." (PMID 40225940, 2024). "Of note, CD4+ helper T cells, B220+ B cells and F4/80+ macrophages also showed a trend towards increased tumor infiltration upon FLT1 blockade in the Brca1-def and Bard1-def models." (PMID 38956205, 2024). "Tumor cell killing by the AF Irofulven depends on the status of BRCA1/2 and Fanconi anemia proteins (FANCD2), which are involved in homology-directed repair of DSBs with Irofulven-induced DSB being considered a replication-associated DNA damage event." (PMID 38630886, 2024). "We determined tumor cell proliferation in vivo and observed that the percentages of Ki-67-positive cells were comparable in p18−/− and p18−/−; Brca1+/− or p18−/−; Gata3+/− tumors." (PMID 38627785, 2024). "Pre- and posttreatment metastatic CRPC (mCRPC) biopsy studies from BRCA1/2 WT tumors, treated on the TOPARP phase II trial, indicated that olaparib eradicated RNASEH2B-loss tumor subclones." (PMID 38833311, 2024). "We further demonstrated that depletion of Gata3 sensitizes tumor cells to PARP inhibitor, and reconstitution of Gata3 enhances resistance of Brca1-deficient tumor cells to PARP inhibitor." (PMID 38627785, 2024). "This case demonstrated an embryonic cell variant of BRCA1 (R71K), as well as sensitivity to PTX plus CBDCA, followed by Ola in maintenance therapy, after a tumor resection in the left iliac fossa." (PMID 38524651, 2024).
tumor (continued). "BRCA1 is a tumor suppressor expressed in all cells and is involved in essential functions required for cell replication and DNA synthesis." (PMID 38159170, 2024). "To visually verify the consistency of interaction signaling molecules between immune cells and tumor cells, we utilized annotated ST data (BRCA1)." (PMID 38254989, 2024). "Impaired HR was usually detected in neoplasm samples, which is related to BRCA1 epigenetic silencing." (PMID 39318358, 2024). "Collectively, these findings indicate that USP4-facilitated BRCA1 stabilization potentially plays a tumor-suppressive role in breast carcinogenesis." (PMID 38734703, 2024). "One possible explanation is that RIF1 function is antagonized by BRCA1 and that BRCA1 is induced at different expression levels in cells, particularly between tumor cells." (PMID 38151954, 2024). "The relevance of the BRCA1/BARD1 ubiquitin E3 activity for tumor suppression and DNA repair remains controversial." (PMID 38769345, 2024). "Adequate reporting and quality monitors are essential to ensure that all centers perform reliable tumor tests to ultimately identify all patients with BRCA1/2 TPVs." (PMID 38730634, 2024). "To determine tumour-specific levels of BRCA1 promoter methylation within samples, we corrected the methylation level by tumour purity and BRCA1 gene-level copy number." (PMID 39055334, 2024). "Recently, ART558, a small POLθ inhibitor, also induced DNA damage and synthetic lethality in BRCA1/2 mutant tumor cells." (PMID 38544832, 2024). "GPR81 can elevate BRCA1 gene expression within tumor cells through the PKC-ERK pathway to aid tumor cells in DNA repair and ultimately lead to tumor chemotherapy resistance." (PMID 38481814, 2024). "For instance, PD-L1 can promote DNA end resection to regulate HR in BRCA1 wild-type tumor cells, enhancing HR repair capacity in tumor cells." (PMID 39156700, 2024). "A copy number pipeline, which employs GRIDSS for joint structural variation calling, confirmed a multiexon in-frame deletion of BRCA1 (chr17:43,096,222–43108182del, p.(K45_S198delinsN)) in all sequenced tumor samples from this patient." (PMID 39101783, 2024). "The current study provides insight into the execution and outcomes of BRCA1/2 tumor analyses in patients diagnosed with advanced-stage EOC in 2019 in the Netherlands." (PMID 38730634, 2024). "The prevalence of gBRCA1m, sBRCA1m, and tumor BRCA1-PM in our cohort was similar to previous studies." (PMID 38191387, 2024). "As a well-known tumor suppressor gene, BRCA1 usually inhibits tumor growth by maintaining genomic integrity." (PMID 39763653, 2024). "BRCA1/2 tumor NGS analyses were performed for 502 patients (50.3%), and a total of 62 TPVs were detected (12.4% of all NGS analyses); 31 TPVs in BRCA1 and 31 TPVs in BRCA2." (PMID 38730634, 2024). "Information on the target enrichment technique applied was missing for a substantial proportion of the performed BRCA1/2 tumor analyses (n = 125, 24.9%)." (PMID 38730634, 2024). "Depletion of Gata3, similar to Brca1 depletion, sensitizes tumor cells to PARP inhibitor-induced cell death." (PMID 38627785, 2024). "This study shows that EOC tumor tests for BRCA1/2 TPV detection were already performed for 50% of all patients before this was officially recommended by national and international guidelines." (PMID 38730634, 2024). "In contrast, there was a significantly smaller proportion of tumours with CRS3 in the germline BRCA1 PV subgroup compared to the germline BRCA1/2 wild type group (OR 0.35, 95% CI 0.14–0.91; P = 0.0291)." (PMID 39550490, 2024).
tumor (continued). "Pathology reports of patients diagnosed with EOC in 2019 in the Netherlands were obtained from the Dutch Pathology Registry (PALGA), and data regarding histological subtype and BRCA1/2 tumor tests were extracted." (PMID 38730634, 2024). "As a tumor suppressor gene, Sirt1 has crucial roles in maintaining heterochromatin structure by deacetylating histones and in regulating Rad5, 1γH2AX, Brca1, and NBS1 foci formation, which are involved in cell cycle checkpoints and DNA damage repair." (PMID 39313797, 2024). "A previous study identified an SVA insertion in BRCA1 intron 2 in a tumor, which led to reduced BRCA1 expression." (PMID 39697868, 2024). "A total of 104 FFPE tissue blocks from patients with EOCs were analyzed for histological type, tumor grade, and BRCA1 protein expression in this study." (PMID 39502381, 2024). "To test this, we analyzed genomes from a diversity of tumor types with driver mutations in either ATM, MEN1, SETD2, BRCA1, BRCA2 and ATRX." (PMID 38909016, 2024). "BRCA1 is a tumor suppressor that is present in all cells and is involved in DNA synthesis, contributing to DNA repair and transcriptional regulation in response to DNA damage." (PMID 38159170, 2024). "Next, PARPi-resistant Brca1-def and Bard1-def tumor cells, transduced with either control lentivirus (“Lenti-Con”), Flt1i lentivirus, or Flt1i lentivirus plus Flt1 o/e lentivirus, were injected orthotopically in the mammary glands of syngeneic B6/129F1 mice." (PMID 38956205, 2024). "From the results it was confirmed that compared to the 4T1 cells-injected groups, CSCs-injected groups showed more metastasis to lungs of tumor-bearing mice, which was denoted by increased BRCA1 expression." (PMID 38796426, 2024). "The study conducted Spearman's partial correlation analysis to explore the relationship between the CA15-3 tumor marker and BRCA1 gene expression across different stages of BC, while controlling for various factors." (PMID 39742378, 2024). "Under normal physiological conditions, the BRCA1/2 gene is tumour suppressor gene and plays an important role in regulating the replication of human cells, the repair of DNA damage and the normal growth of cells." (PMID 39530091, 2024). "As BRCA1 is a known activator of tumor suppressor genes, in orthotopic tumor region of mammary fatpad of both 4T1 cells and CSCs injected mice, expression of BRCA1 was reduced in DOX treated groups compared to the controls." (PMID 38796426, 2024). "One group, characterized by high sTILs and tumor BRCA1-PM, showed excellent 15-year OS and DRFS, while the other group, characterized by low sTILs and gBRCA1m showed poor 15-year OS and DRFS." (PMID 38191387, 2024). "BRCA1 is a tumor suppressor gene which plays a critical role in HR-mediated DNA double strand break (DSB) repair." (PMID 38976671, 2024). "Patients (n = 66) with tumor BRCA1-PM and sTILs ≥ 50% showed excellent 15-year OS (97.0%, 95% CI, 92.9–100%), while patients (n = 61) with gBRCA1m and sTILs < 50% showed poor 15-year OS (50.8%; 95% CI, 39.7–65.0%)." (PMID 38191387, 2024).
tumor (continued). "For HOXA1, no significant age-related differences were observed (P=0.4329), but significant differences were found in tumor size, histology, clinical stage, ER status, and BRCA1 status." (PMID 39267845, 2024). "Out of the 30 tumors examined, methylation of the BRCA1 promoter was found in 76.6% (23 cases), with all 23 tumor samples exhibiting a positive methylated reaction." (PMID 39246954, 2024). "The main tumor susceptibility genes in CBC3T-1 cells included BARD1, KDR, FAT1, HNF1A, BRCA2, FANCA, and BRCA1." (PMID 37966669, 2024). "Combined use with STING (stimulator of interferon genes) agonists can further enhance persistent tumor regression in BRCA1/2 wild-type TNBC mouse tumor models, significantly improving survival outcomes." (PMID 39156700, 2024). "Following this validation exercise, we were able to show a trend towards omental CRS3 in tumours harbouring a germline BRCA2 PV compared to tumours with germline BRCA1/2 wild type." (PMID 39550490, 2024). "In cases where a tumor arises from a cell with a BRCA1 epimutation in an individual with a low level of BRCA1 methylation, one would expect to see a clonal expansion into a tumor revealing a much higher VEF, in addition to LOH." (PMID 40225940, 2024). "Eleven patients displayed a BRCA1/2 wildtype in the germline and tumor DNA, equally distributed amongst the two PARPi response groups." (PMID 38927686, 2024). "We found a strong correlation between BRCA1 and some invasive clinical features, such as tumor size, lymph node involvement." (PMID 38224491, 2024). "Total proteins were extracted from a piece of the tumor to evaluate BRCA1 expression by Western blotting." (PMID 38589490, 2024). "We observed significantly slower tumor growth kinetics in ID8Trp53−/−;Brca2−/−-bearing mice compared with ID8Trp53−/−- and ID8Trp53−/−;Brca1−/−-bearing mice." (PMID 39028933, 2024). "In this substudy, immune biomarkers (PD-L1 expression on immune cells and tumor cells, intratumoral CD8, stromal TILs) and germinal BRCA1/2 alterations were evaluated for association with clinical benefit with atezolizumab and nab-paclitaxel." (PMID 37444415, 2023). "On Cox regression analysis, longer OS was associated with increased duration of platinum-based therapy (HR 0.98, 95% CI 0.95–0.99, p = 0.04), while adjusting for tumor site, HRD and SBS3 scores, and BRCA1/2 mutation status." (PMID 36964191, 2023). "As for patients harboring BRCA1 methylation in both tumor and WBC, BRCA1 methylation levels in the tumors were 36–103 fold higher than in blood, consistent with clonal expansion of cells with methylated BRCA1 alleles." (PMID 38053165, 2023). "In total, 17 out of 66 (25.8%; 95% CI 15.8–38.0) patients with TNBC harbored tumor BRCA1 methylation." (PMID 38053165, 2023). "The two main ones include: (i) sequencing of key DNA repair genes, such as BRCA1, BRCA2 or PALB2, to identify pathogenic variants, both germline and somatic, (ii) quantifying HRD-associated genomic features in tumor DNA, with often these two combined." (PMID 36805632, 2023). "It was revealed that the BRCA1 expression level increased along with the elevation of Olaparib dose in these cell lines which was also explicable that tumor cells strengthened the ability to repair DNA damage by upregulating BRCA1 when PARP was inhibited." (PMID 37864041, 2023). "The role of BRCA1 as the guardian of genome stability is thought to account for the tumor-suppressive function of BRCA1 and some of its partners (i.e., BRCA2)." (PMID 37887275, 2023). "The primary mechanism behind this effect is attributed to the formation of BRCA1 nuclear foci, which in turn triggers the accumulation of γH2AX, causing DSB, and ultimately resulting in the demise of tumor cells." (PMID 37958290, 2023).
tumor (continued). "The overexpression of BRCA1 was an independent risk factor for LUAD and was indicative of an immune‐suppressive tumor microenvironment." (PMID 38090061, 2023). "A statistically significantly lower percentage of RAD51+/GMN+ and BRCA1+/GMN+ tumor cells were observed in VLS than in VSS; a similar percentage of γH2AX+/GMN+ cells were found in both patient subgroups." (PMID 37686585, 2023). "This study analyzing BRCA1, BRCA2, and PALB2 mutations through tumor-targeted sequencing boosts several notable strengths." (PMID 38098088, 2023). "In this group, 29.2% of tumors were BRCA1-methylated, and 19.4% harbored concordant tumor and WBC methylation." (PMID 38053165, 2023). "Tumour and germline BRCA1/2 testing can be performed in parallel (i.e., together) or sequentially (i.e., germline-first then tumour, or tumour-first then germline)." (PMID 38201604, 2023). "Considering both the tumor and the adjacent tissue samples, the ratio between circRNAs and mRNAs was 1.36 and 0.23 circular junctions per 100 linear junctions for BRCA1 and BRCA2, respectively." (PMID 37046838, 2023). "Endometrioid tumours of well-differentiated grade provided evidence against VUS pathogenicity for BRCA1 (LR: 0.12 (95% CI: 0.04–0.31), moderate evidence) and BRCA2 (LR: 0.31 (95% CI: 0.12–0.84), supporting evidence)." (PMID 37076566, 2023). "We, thus, evaluated the percentage of RAD51 foci/geminin-positive (RAD51+/GMN+) cells and BRCA1 foci/geminin-positive (BRCA1+/GMN+) cells in the FFPE tumor samples of the same patients." (PMID 37686585, 2023). "A known driver of CIN is defective DNA damage repair, and in the case of HGSOC, possibly up to 50% are homologous recombination deficient (HRD), frequently caused by mutations in the BRCA1 and BRCA2 tumour suppressor genes." (PMID 37592171, 2023). "If tumour genetic testing was performed, the panellists considered further germline testing appropriate in patients with high-volume mHSPC (CHAARTED criteria) having a BRCA1/2 tumour (L)PV or a non-BRCA1/2 tumour (L)PV (eg, ATM, CHEK2)." (PMID 36874601, 2023). "Homologous recombination deficiency due to mutational inactivation of the BRCA1 and BRCA2 tumor suppressor genes is known to make human tumors susceptible to PARP inhibitors and platinum-based chemotherapies." (PMID 37906280, 2023). "DNA double-strand break repair by homologous recombination (HR) is one of the primary mechanisms by which BRCA1 works as a tumor suppressor." (PMID 37109525, 2023). "•The BGCS refers for parallel tumor and germline testing for BRCA1 and BRCA2 with a preference to offer testing as early in the patient journey as possible." (PMID 37181681, 2023). "The BARD1 protein interacts with BRCA1 and is thought to play a critical role in BRCA1-mediated tumour suppression." (PMID 36980802, 2023). "BRCA1 is a tumor suppressor, and a recent study found that overexpression of BRCA1 reduced reactive oxygen species production and lipid peroxidation after IS to increase DNA repair." (PMID 37794518, 2023). "Firstly, it was questioned which genes the tumor DNA test should cover in addition to BRCA1 and BRCA2, since the germline test panel includes more OC risk genes." (PMID 35570228, 2023). "Following intravenous delivery, compared to NP only control group, mice treated with BRCA1 plasmid + NP exhibited reduced trend for development of tumor and the difference was significant at day 14, day 16, day 18, day 20 and day 22; where *p < 0.05." (PMID 36631481, 2023). "MS-MLPA analysis performed on tumor tissue samples showed that BRCA1 promoter hypermethylation was present in five samples (17%), while no samples showedBRCA2 promoter hypermethylation." (PMID 36900320, 2023).